CCND1 (cyclin D1)
Diseases named in the same sentence as CCND1 in open-access papers (continued):
Sharing a sentence is not in itself a finding about the gene and the disease.
colon carcinoma (continued). "PKCα acts as a tumor suppressor in intestinal epithelial cells via downregulation of cyclin D1, while PKCε appears to function as an oncogene in both transformed IEC-18 and colon cancer cells via positive regulation of cyclin D1." (PMID 36675501, 2023). "Chaga-derived ergosterol peroxide was shown to decrease the transcription of C- Myc, cyclin D1, and CDK-8 and ultimately reduced the growth of colonic tumors in mice." (PMID 37153767, 2023). "Upregulation of Cyclin D1, p‐PKA, c‐Myc, and proteins that regulate the cell cycle was occurred, followed by NP treatment in colon cancer cells." (PMID 36207986, 2023). "FXR-KO mice exhibited elevated colon cancer markers (β-catenin, LGR5, CD44, CD34, and cyclin D1) under LPS, underscoring the pivotal role of FXR in inhibiting the development of colon tumorigenesis." (PMID 38069256, 2023). "And some studies have shown that the knockout of IGF2BP3 can inhibit DNA replication and angiogenesis in the S phase of the cell cycle by reading the m6A modification of CCND1 and vascular endothelial growth factor (VEGF) respectively in colon cancer." (PMID 36793593, 2023). "The reduced number of colonic tumors in the ID + AOM/DSS and IOL + AOM/DSS groups was accompanied by the downregulated expression of cell proliferation regulators (PCNA, cyclin D1, and c-Myc)." (PMID 35631174, 2022). "We also observed a dose-dependent decrease in the levels of cyclin D1 in MakA-treated DLD1 and CT26 colon cancer cells." (PMID 36473840, 2022). "In human colon cancer cells, inhibiting IDO1 activity reduced nuclear and activated β-catenin, transcription of its target genes such as cyclin D1, and, ultimately, proliferation." (PMID 35918736, 2022). "CD155 also affects the activation of AKT in colon cancer; in CT26 and Sw620 colon cancer cells, the knockdown of CD155 inhibits the expression of Cyclin D1 and CDK4, inducing the arrest of the cell cycle in G1, further suppressing the growth of tumor cells." (PMID 36358792, 2022). "In human colon cancer cells, diminished IDO1 activity reduced nuclear and activated β-catenin, transcription of its target genes (cyclin D1 and Axin2), and, ultimately, proliferation." (PMID 35918736, 2022). "FN suppresses cell proliferation and invasion by inhibition of cyclin D1 and MMP2/9 expression via p-STAT3 inactivation in colon carcinoma cells." (PMID 34539403, 2021). "Cyclin D1 and LEF-1 (Lymphoid Enhancer Binding Factor 1) are overexpressed in colon cancer and have been identified as the target genes of miR-449a in human prostate cancer and mesenchymal stem cells." (PMID 34737955, 2021). "Conversely, expression of cyclin D1 and cyclin E1 increases after knockdown of SLFN11 in DKO colon cancer cells that express high endogenous SLFN11." (PMID 34571887, 2021). "The results showed that the high expression of CCND1 and VEGFA was significantly correlated with poor prognosis of colon cancer (p < 0.05)." (PMID 34922547, 2021). "Among the four datasets of colon cancer from The Cancer Genome Atlas and the Gene Expression Omnibus, six cyclin genes (CCNA2, CCNB1, CCND1, CCNE1, CCNF, and CCNJL) were differentially expressed between normal and tumor tissues." (PMID 33996604, 2021). "The ABCB1 molecular transporter is also an indirect target of miR-506, a negative regulator of CTNNB1 and cyclin D1 (CCND1), and promotes L-OHP sensitivity in colon cancer after forced expression." (PMID 34503164, 2021). "Bacillus polyfermenticus treatment reduced ErbB2, ErbB3, cyclin D1, and E2F-1 transcription factor in HT-29, DLD-1, and Caco-2 colon cancer cells." (PMID 34992527, 2021).
colon carcinoma (continued). "In the present study, we identified that Zic2 enhances Wnt signaling and initiates the transcription of several novel downstream target genes, including cyclin D1, CD44, and Lgr5, which promote proliferation and stemness in colon cancer cells." (PMID 34099631, 2021). "The analysis of the expression of cell cycle regulators revealed that 8-hydroxyquinaldic acid inhibited the expression of cyclin D1 and CDK4 in both colon cancer cell lines." (PMID 32260268, 2020). "The results show that TDZs can induce the degradation of cyclin D1 and CDK4, and the expression of p21 and p27, which is consistent with their inhibition of G1 to S-phase progression in colon cancer cells." (PMID 32170185, 2020). "It has been reported that decursin, which is derived from Angelica gigas Nakai, can decrease cyclin D1 and CDK4 expression in 253J human bladder cancer cells and HCT116 human colon cancer cells." (PMID 32349276, 2020). "LncRNA small nucleolar RNA host gene 7 (SNHG7) is overexpressed in colon advanced adenomas and early-stage colon cancer, and SNHG7 downregulation in HT29 cells retards cell proliferation via interacting with miR-193b and suppressing K-ras/ERK/cyclin D1." (PMID 33246471, 2020). "Western blot assay showed that downstream targets of Wnt signaling, including β-catenin, cyclin D1 and c-myc, were up-regulated or down-regulated in CDX2-knockdown or CDX2-overexpressing colon cancer cells." (PMID 30631044, 2019). "Curcumin has been found to down regulates cyclin D1 and induced G1 cell cycle arrest in HCT-116 colon cancer cells." (PMID 31108984, 2019). "Curcumin was found to activate PPARγ and suppressed the growth of both HT-29 colon cancer cells and Moser cells following inhibition of EGFR and cyclin D1 expression." (PMID 31108984, 2019). "Our results showed that siHuR decreased transcriptional expressions of galectin-3, β-catenin, cyclin D1, Bcl-2, P-gp, MRP1, and MRP2 in epirubicin-treated colon cancer cells." (PMID 28968471, 2017). "When we treated two HCC cells and two colon cancer cells with siRNA for SMYD2 (siSMYD2), significant downregulation of both CCND1 and cMYC was observed in concordance with the decrease of nuclear β-catenin in all of these four cell lines." (PMID 28915556, 2017). "Our most recent studies show that RING domain of XIAP is crucial for XIAP upregulation of Cyclin D1 expression, while BIR domains specifically mediate E2F1 transactivation and Cyclin E expression in human colon cancer HCT116 cells." (PMID 27447744, 2016). "Recently, CGK733 has been shown to induce cell death in breast, lung, and colon carcinoma cells by modulating ATM, p21 (CIP1) and cyclin D1." (PMID 26259235, 2015). "Three (MYC, CCND1 and CD44) of the six downstream targets were reported to be transcriptionally regulated by the Wnt signaling in the colon carcinoma cells from which the HCT 116 (the cell line we used in this study) was derived." (PMID 26057633, 2015). "In our previous study using colon carcinoma cells, NDRG2 modulated the cell cycle via phosphorylation of c-Jun and the down-regulation of AP-1 and cyclin D1." (PMID 25061501, 2014). "Considering that cyclin D1 and c-Myc are related to cell cycle regulation, we examined the effect of DACT1 overexpression and silencing on cell cycle regulation in colon cancer cells." (PMID 22470507, 2012). "In an additional study CCND1 was the isoform that was sensitive to CDK inhibition, seliciclib resulted in a decrease in its expression in colon cancer cells." (PMID 22558078, 2012). "In human colon cancer cells, PDGF-BB induces EMT and upregulates cyclin D1 and c-Myc by activating β-catenin-dependent gene expression." (PMID 22276222, 2012).
colon carcinoma (continued). "In a converse experiment, the forced expression of LPP3 in human colon tumor (SW480) cells potentiated tumor growth via increased β-catenin stability and CYCLIN-D1 synthesis." (PMID 21569306, 2011). "Repression of the β-catenin/TCF transcriptional targets Cyclin D1 and c-Myc were observed in cells transfected with PTK6 YF (- ALT-PTK6), similar to what we previously observed in the SW620 colon cancer cell line." (PMID 21479203, 2011). "Tetsu and McCormick reported that expression of cyclin D1 is strongly dependent on β-catenin/TCF and has a direct effect on cell proliferation in colon carcinoma cells." (PMID 17922924, 2007). "The natural metabolites hypothemycin (0.5 μg/Ml) and O-methyl deoxybouvardin (RA-VII) (100 nM) have also been shown to induce the ubiquitin-dependent degradation of cyclin D1 in transformed NIH3T3 mouse and human colon cancer cell lines respectively." (PMID 17407548, 2007). "Aspirin was recently reported to induce the p38SAPK2 dependent degradation of cyclin D1 in SW480 and HT-29 colon cancer cells." (PMID 17407548, 2007). "The impact of these findings may extend beyond MCL, as cyclin D1 overexpression is seen in about 10%–20% of NHL and other hematologic malignancies; in solid tumors, including 50% of breast and colon cancers; and in 80% of pancreatic cancer." (PMID 40608419, 2025). "Additionally, TAGP lowered the levels of Cyclin D1 and c-Myc, which are regulated by β-catenin/T-cell factor (TCF) and showed antiproliferative activity in colon cancer cells." (PMID 40730487, 2025). "Our results indicated that IRSp53 is a substantial aim in colon cancer remedy and secretome of hAMSCs suppresses IRSp53 expression as well as related molecules such as IRSp53, p-AKT (Ser 473), p-Stat3 (Tyr 705), and cyclin D1 in the HT-29 colon cancerous cell line." (PMID 41200137, 2025). "In detail, research has revealed that ginsenoside Rg3 disrupts the cell cycle at G0/G1 phase via the EGFR/Ras/Raf/MEK/ERK pathway in lung cancer (A549), liver cancer (Hep G2) cells, and the formation of Cyclin D1, CDK2, and CDK4 in colon cancer (SW620 and LoVo) cells." (PMID 40490812, 2025). "exhibited cytotoxicity against various human colon cancer cells and induced G0/G1 phase cell cycle arrest in HCT116 human colon cancer cells via downregulation of cyclin D1 through phosphorylation-dependent ERK1/2, p38 or GSK3β, and cyclin D1 transcriptional inhibition through Wnt signaling." (PMID 38966207, 2024). "Interestingly, in colon cancer cell lines, we found that increasing intracellular miR-195-5p was able to reduce the protein expression levels of NLK, LEF1 and Cyclin D1 via JUP modulation." (PMID 38069408, 2023). "Additionally, TSL suppressed the proliferation of colon cancer cells via the downregulation of Wnt target genes, such as CCND1 (cyclin D1) and MYC (c-myc) and decreased the cell viability in the MTT assay." (PMID 35053565, 2022). "Similarly, in colon cancer, the silencing of IDO1 inhibits the expression of β-catenin in the nucleus, as well as the expression of Axin2 and Cyclin D1, further exerting an inhibitory effect on tumor proliferation." (PMID 36358792, 2022). "Consistently, CCNA2, CCNB1, CCND1, and CCNF have been observed to be upregulated in colorectal cancer, but there is no clear evidence that CCNE1 and CCNJL are also differentially expressed between colon tumor and normal tissues." (PMID 33996604, 2021). "Moreover, the expression of active caspase‐3, p21 and E‐cadherin was up‐regulated and the expression of cyclin D1, c‐Myc, vimentin, N‐cadherin and MMP9 was down‐regulated in OCA‐treated colon cancer cells." (PMID 33164339, 2020). "Lentiviral vector-mediated IL-9 overexpression in the colon cancer cells lines RKO and Caco2 could promote the proliferation of colon cancer cells by upregulating the expression of c-myc and cyclin D1." (PMID 32228589, 2020).
colon carcinoma (continued). "Furthermore, we also proved the positive relationships between the expression levels of CASC21 and co‐expressed cell cycle‐related genes including CCND1 and CDK4 by RNA sequencing using 20 colon cancer tissues." (PMID 31965704, 2020). "There were clues that TSL suppresses colon cancer cell proliferation by inhibition of β-catenin-dependent Wnt pathway and decreased the expression of cyclin D1 and c-myc, but there was no research about TSL in angiogenesis so far." (PMID 31333473, 2019). "Rat colon tumors exposed to sulindac and naproxen individually or in combination with atorvastatin showed significant suppression of PCNA, cyclin D1 and β-catenin and reduced key inflammatory markers, inducible NOS and COX-2, p65, as well as inflammatory cytokines, TNF-α, IL-1β, and IL-4." (PMID 30096840, 2018). "Here we show that IRS-1 regulates expression of cyclin D1 and XIAP in colon cancer cells." (PMID 28414818, 2017). "Among them, β-catenin is critical in regulating Wnt signaling pathway by entering the nucleus and binding to T-cell factor/lymphoid enhancer factor (TCF/LEF) and activating their specific target genes including c-Myc, cyclin D1, MDR1 in colon cancer and chronic myeloid leukemia (CML) cells." (PMID 28968471, 2017). "Given their function in regulating cell cycle and survival, effects on cyclin D1 and XIAP may contribute to IRS-1 mediated enhancement of cell proliferation and inhibition of apoptosis in colon cancer cells." (PMID 28414818, 2017). "To study whether miR-374a suppresses PI3K/AKT pathway via directly reducing CCND1 in colon cancer, we transfected HCT116 and SW620 cells with two sequences of si-CCND1 or control." (PMID 27191497, 2016). "Further, we analyzed the negative correlation between miR-374a and CCND1 expression in colon cancer patients, finding this pattern was closely related with prognosis." (PMID 27191497, 2016). "They concluded that CCND1 rs9344 may be a predictive and/or prognostic biomarker in stage II/III colon cancer patients." (PMID 26884752, 2016). "Considering cyclin D1 proto-oncogene is ultimately important to modulate the transition of G1 to S phase in various cell types, XNT reduced cyclin D1 expression in HCT116 colon cancer, TE-1 and TE-4 esophageal squamous cancer cell lines." (PMID 26500452, 2015). "Treatment of DLD1 and Ls174T colon cancer cellsin vitro with Ivermectin led to a dose-dependent inhibition of the levels of two C-terminal phosphoforms of β-CATENIN: Phospho-Ser552 and Phospho-Ser675 and to the repression of CYCLIN D1 (Fig6A)." (PMID 25143352, 2014). "We have shown here that T-Antigen and β-catenin physically interact in the nuclei of colon cancer cells and that this stabilization leads to the activation of TCF-dependent transcription as measured by TOPflash activity and c-Myc and Cyclin D1 promoter activation." (PMID 25229241, 2014). "Importantly, we confirmed that Kaiso also associated with the −1067, +69 core KBS and CpG regions of the cyclin D1 promoter in vivo in both MCF7 breast and HCT 116 colon carcinoma cells." (PMID 23226276, 2012). "Colon cancer cell growth inhibition was accompanied by downregulation of Sp1, Sp3 and Sp4 proteins and decreased expression of Sp-regulated gene products including bcl-2, survivin, VEGF, VEGFR1, cyclin D1, c-MET and p65 (NFκB)." (PMID 23110215, 2012). "Furthermore, consistent with our current data in HNSCC, we have previously shown, in both cell culture and animal models of colon cancer, that PEG-induced EGFR downregulation suppressed proliferation potentially through cyclin D1." (PMID 22675506, 2012). "Moreover, knockdown of Sp1, Sp3 and Sp4 (in combination) in RKO colon cancer cells also decreased expression of EGFR, cyclin D1, p65 and PTTG-1, confirming the role of Sp transcription factors in regulating expression of these genes." (PMID 21864401, 2011).
colon carcinoma (continued). "In breast, sarcoma and colon cancers, with cyclin D1 overexpression and no chromosome 11 alterations, elevated mRNA levels result from a trans-acting influence of both alleles." (PMID 17022831, 2006). "We found that cyclin D1 overexpression is distributed equally among various TMN-stage tumours, which indicates that in colon cancer, the overexpression of cyclin D1 is not related to the metastatic status of the tumour." (PMID 16012517, 2005). "Furthermore, the protein levels of PCNA protein (a marker for cell proliferation), cyclin D1 and cyclin E (key regulators of the cell cycle), and MMP-9 (a key regulator of metastasis in colon cancer), as well as TNFα (a marker for extrinsic cell apoptosis) in nude mice were measured by IHC." (PMID 36979011, 2023). "Furthermore, in colon cancer, the internalized CD44 and acetyltransferase p300 induce STAT3 acetylation at Lysine (Lys) 685, which in turn promotes the expression of cell cycle regulators cyclin D1 70, MYC, and Twist1 in colon cancer cells." (PMID 32754274, 2020). "Like c-MYC and cyclin D1, ITF-2 functions as an oncogene when deregulated in human colon cancer or ovarian cancer, although other studies have reported that the inactivation of ITF-2 may play a role in early gastric carcinoma progression or in the colonic adenoma to carcinoma transition." (PMID 28574827, 2017). "However, in human colon carcinoma RKO cells, which have a normal β-catenin destruction complex, negatively affected β-catenin-mediated transcriptional activity, cell proliferation, and the expression of Wnt target genes C-MYC and CYCLIN D1." (PMID 23520519, 2013). "Thus, expression of β-catenin, Cyclin D1, and Mmp7 remained high in adenomatous polyps compared to normal colon, and was unaffected by SPI3d or SPI treatment, although SPI increased cleaved PARP and Caspase–3 in Pirc colon tumors, indicative of apoptosis induction." (PMID 35159382, 2022). "Interestingly, the effect of Schlafens on colon cancer extends beyond the human Schlafens, as exogenous expression of mouse Slfn3 in human CRC cell lines that lack Slfn3 induces G0/G1 arrest by downregulating Cyclin D1 expression and reducing phosphorylation of retinoblastoma (pRB) protein." (PMID 34571887, 2021). "(H) qRT-PCR for Axin2, Ccnd1, Myc, and Ctnnb1 in HCT116 colon cancer cells treated with miR-31 inhibitor and negative control (NC, Scramble RNA), as well as miR-31 mimics and negative control (NC, Scramble RNA) for 24 hrs." (PMID 28870287, 2017). "Additional findings supporting this mechanism included reduced colon tumor formation in muscarinic agonist-treated mice lacking intestinal epithelial cell βPix expression and reduced MYC, CCND1 and PTGS2 gene and protein expression in colon adenocarcinomas resected from those mice." (PMID 39493347, 2024). "Consistently, VSTM2A significantly inhibited the expression of Wnt target genes cyclin D1 and c-myc, and β-catenin activation, but did not change β-catenin mRNA expression in 293T and RKO cells, suggesting secreted protein VSTM2A negatively regulated Wnt signaling pathway in colon cancer." (PMID 31588233, 2019).